WDR6 (WD repeat domain 6)
Description:
Together with methyltransferase FTSJ1, methylates the 2'-O-ribose of nucleotides at position 34 of the tRNA anticodon loop of substrate tRNAs. Required for the correct positioning of the substrate tRNA for methylation. Required to suppress amino acid starvation-induced autophagy. Enhances the STK11/LKB1-induced cell growth suppression activity.
Synonyms: Trm734
Tractability: Antibody: its Gene Ontology location is reachable by antibodies, with high confidence. PROTAC: ubiquitination databases record sites on it; its protein half-life has been measured.
Gene: Protein-coding gene on chromosome 3 (49,007,062 to 49,015,953, forward strand). Ensembl gene ENSG00000178252.
Subcellular location: Cytoplasm
Subcellular location (Human Protein Atlas): Cytosol; Plasma membrane
Pathways (Reactome):
Signal Transduction: RHOU GTPase cycle; RHOV GTPase cycle; RND1 GTPase cycle; RND2 GTPase cycle; RND3 GTPase cycle
Gene Ontology:
Molecular function: enzyme regulator activity; enzyme-substrate adaptor activity; protein binding; RNA binding; tRNA binding
Biological process: G1 to G0 transition; negative regulation of autophagy; negative regulation of cell population proliferation; wobble position ribose methylation; tRNA methylation
Cellular component: COP9 signalosome; cytoplasm; cytosol
Genetic constraint (gnomAD): Loss-of-function variants: 58 observed, 88.52 expected, observed/expected ratio (o/e) 0.66, 90% interval 0.53 to 0.81. The upper end of that interval is the gene's LOEUF score, 0.81, which puts it in group 3 of 6, group 1 being the genes least tolerant of losing a copy. Missense variants: 1,310 observed, 1,544.9 expected, observed/expected ratio (o/e) 0.85, 90% interval 0.81 to 0.89. Synonymous variants: 569 observed, 608.77 expected, observed/expected ratio (o/e) 0.93, 90% interval 0.87 to 1.
Homologues: Orthologues: chimpanzee WDR6 (99% identical), macaque WDR6 (98% identical), dog WDR6 (93% identical), pig WDR6 (92% identical), rat Wdr6 (89% identical), guinea pig WDR6 (88% identical), mouse Wdr6 (87% identical), rabbit WDR6 (76% identical), tropical clawed frog wdr6 (41% identical), zebrafish wdr6 (35% identical), Drosophila melanogaster CG33172 (19% identical).
Diseases named in the same sentence as WDR6 in open-access papers:
WDR6 is named in the same sentence as 45 diseases in open-access papers, as found by Europe PMC text mining. Sharing a sentence is not in itself a finding about the gene and the disease. The quoted sentences say what the papers report.
Crohn disease (2 papers, 2023 to 2025). A gastrointestinal disorder characterized by chronic inflammation involving all layers of the intestinal wall, noncaseating granulomas affecting the intestinal wall and regional lymph nodes, and transmural fibrosis. "Our findings establish WDR6 as a cross-disorder risk gene consistently associated with Crohn’s disease, ulcerative colitis, and major depressive disorder." (PMID 41595424, 2025).
lung carcinoma (2 papers, 2022 to 2023). "WDR6 can be used as a prognostic marker for lung cancer and is significantly associated with immune cell infiltration." (PMID 36039642, 2022). "For the first time, our results manifested that the high‐expression level of WDR6 was associated with a good prognosis, and further indicated that WDR6 could serve as a good prognostic biomarker to diagnose and treat lung cancer." (PMID 36039642, 2022). "In this part, we further investigated whether WDR6 expression was associated with immune cell infiltration in lung cancer patients, finding that the expression of WDR6 obviously related to CD8+ T cell and CD4+ T cell in LUAD, while only correlated with CD4+ T cell in LUSC." (PMID 36039642, 2022). "In a previous study, we used the expression of WDR6 (WD repeat domain 6) between pan-cancer and normal tissue by employing the bioinformation analysis and exploring the immunological and prognostic role in lung cancer patients." (PMID 36846347, 2023). "This study first offers a relatively comprehensive understanding of the oncogenic roles of WDR6 for lung cancer." (PMID 36039642, 2022). "We found that High WDR6 expression predicted better OS and FP in both male and female lung cancer patients." (PMID 36039642, 2022). "The overall survival, first progression, postprogression survival, and Relapse‐free survival of lung cancer patients were longer in the WDR6 high‐expression group than in the low‐expression group." (PMID 36039642, 2022). "In brief, we concluded that WDR6 is a prognostic molecular biomarker for good survival correlated with immune cell infiltration in lung cancer." (PMID 36039642, 2022). "In this study, we first explored the prognostic and immunological role of WD repeat domain 6 (WDR6) on lung cancer based on the public datasets." (PMID 36039642, 2022). "The results concluded that there is a possible novel prognostic molecular marker for good survival correlated with immune cell infiltration in lung cancer, called WDR6 expression." (PMID 36039642, 2022). "As for early‐stage lung cancer, such as T1, T2, N0, or N1, the role of WDR6 expression on survival prognosis showed a more significant effect." (PMID 36039642, 2022). "We found the expression of WDR6 significantly correlated with immune molecules, including immunomodulators, lymphocytes, and chemokines in lung cancer." (PMID 36039642, 2022). "We also found that the DSS of lung cancer patients in the WDR6 high‐expression group were lengthened compared to the low‐expression group, which WDR6 could served as a specific factor for disease‐specific survival." (PMID 36039642, 2022). "The data of this part indicated that WDR6 could be a novel and prognostic biomarker for tumor diagnosis and therapy in lung cancer patients, especially for early LUAD." (PMID 36039642, 2022). "Therefore, it was confirmed that WDR6 participated widely in modulating various immune molecules in lung cancer patients especially LUAD to affect immune infiltration in the tumor microenvironment (TEM)." (PMID 36039642, 2022). "Followingly, we further investigated the relationship between WDR6 expression and immune‐infiltrating cells in the TEM, and the results showed that WDR6 expression significantly correlated with immune‐infiltrating cells and their gene markers in lung cancer patients." (PMID 36039642, 2022). "Our study used Oncomine, TIMER2.0, GEPIA2, Kaplan–Meier plotter, PrognoScan, and TISIDB tools to analyze the differential expression between pan‐cancer, especially lung cancer, and corresponding normal tissue, and further explore the prognostic and immunological role of WDR6 expression." (PMID 36039642, 2022). "All survival analysis data from the Kaplan−Meier plotter data set of this part manifested that WDR6 could be a potential and poor prognostic factor for gastric cancer and ovarian cancer patients, but a better prognostic biomarker for breast cancer and lung cancer patients." (PMID 36039642, 2022).
lung carcinoma (continued). "However, there are no relevant studies on the effect of WDR6 expression on the prognosis of cancer patients, especially lung cancer." (PMID 36039642, 2022).
colorectal cancer (1 paper, 2022). A primary or metastatic malignant neoplasm that affects the colon or rectum. "In addition, WDR6 was found to be a possible target gene of miR‐451a in colorectal cancer and might play a crucial role in tumor regulation." (PMID 36039642, 2022).
Hepatic steatosis (1 paper, 2023). Steatosis is a term used to denote lipid accumulation within hepatocytes. "WDR6 contributes to promoting hepatic de novo lipogenesis during insulin resistance by upregulation of fatty acid synthase, and the authors identify a small molecule to inhibit this effect of WDR6 and reduce hepatic steatosis." (PMID 37735236, 2023). "Together, these results reveal WDR6 as a promising target for the treatment of hepatic steatosis." (PMID 37735236, 2023). "We also identified a small molecule that could block the relevant effects of WDR6 and thus reduce hepatic steatosis during IR." (PMID 37735236, 2023). "Together, these results point to a role for WDR6 in elevated DNL under IR states and suggest a potential therapeutic avenue to reduce fatty liver disease." (PMID 37735236, 2023).
hepatocellular carcinoma (1 paper, 2020). A malignant tumor that arises from hepatocytes.
inflammatory bowel disease (1 paper, 2025). A spectrum of small and large bowel inflammatory diseases of unknown etiology. "For instance, in inflammatory bowel disease, it is hypothesized that altered WDR6 function could contribute to impaired autophagy, thereby affecting intestinal barrier integrity and immune homeostasis." (PMID 41595424, 2025).
lung adenocarcinoma (1 paper, 2022). A carcinoma that arises from the lung and is characterized by the presence of malignant glandular epithelial cells. "Our results showed WDR6 was lower expressed in lung squamous cell carcinoma than in normal tissue, but WDR6 expression was correlated obviously with clinical stage in Lung adenocarcinoma." (PMID 36039642, 2022).
major depressive disorder (1 paper, 2025). An episode of depression lasting two or more weeks without an intervening episode of mania. "Similarly, in major depressive disorder, it is possible that dysregulated WDR6 activity might disturb neural plasticity and stress response pathways." (PMID 41595424, 2025).
cancer (3 papers, 2022 to 2023). A tumor composed of atypical neoplastic, often pleomorphic cells that invade other tissues. "To further study the effect of WDR6 on prognosis in pan‐cancer, we also analyzed the survival data from Kaplan−Meier plotter and PrognoScan databases between the WDR6 high‐expression group and WDR6 low‐expression group." (PMID 36039642, 2022). "The relationship between WDR6 expression and chemokines in pan‐cancer was presented by heatmap, and especially, the top 3 scatter plots of the absolute p values showed the negative and significant correlation of the two in LUAD and LUSC." (PMID 36039642, 2022). "To further verify the effect of WDR6 gene expression on prognosis, we employed the data from the PrognoScan database to investigate whether WDR6 expression could lead to a better prognosis for special types of cancers." (PMID 36039642, 2022).
tumor (3 papers, 2019 to 2023). "Compared with the control group, WDR6‐KO mice showed an immune profiling with less tumor‐suppressive polymorphonuclear myeloid‐derived suppressor cells (PMN‐MDSC, CD11b+Ly6G+Ly6Clo) recruitment, but higher T‐cell counts." (PMID 36947051, 2023). "Interestingly, the levels of WDR6 protein and mRNA progressively increased from normal hepatocyte cells to highly metastatic tumor cells." (PMID 36947051, 2023). "We demonstrate that WDR6 promotes HCC progression by enhancing ubiquitination‐dependent degradation of tumor suppressor UV radiation resistance‐associated gene (UVRAG), thereby fostering an immunosuppressive and prometastatic tumor microenvironment." (PMID 36947051, 2023). "Furthermore, immunohistochemical staining (IHC) using clinical HCC samples (n = 201) revealed that enhanced WDR6 expression levels were significantly related to increased tumor size, vascular invasion, and distant metastasis." (PMID 36947051, 2023). "Thus, WDR6 may be an unknown regulator critical to tumor progression." (PMID 36947051, 2023). "Precise targeting of the WDR6/UVRAG‐related pathological activity offers the advantage of minimizing potential undesirable side effects, which is of paramount importance for tumor therapy." (PMID 36947051, 2023).
metabolic disorders (1 paper, 2023). "Taken together, these data show that liver-specific inhibition of Wdr6 ameliorates, or reverses, metabolic disorders during IR, especially liver lipid deposition, while Wdr6 overexpression has the opposite effects." (PMID 37735236, 2023).
neurodevelopmental disorder (1 paper, 2020). A behavioral and cognitive disorder with onset during the developmental period that involves impaired or aberrant development of intellectual, motor, or social functions. "Importantly, CG33172, TRM734 and WDR6 are members of the WD40-repeat-containing domain superfamily that contains also the human protein WDR4, another tRNA-MTase cofactor that, like FTSJ1, when mutated is associated with neurodevelopmental disorders." (PMID 31943105, 2020).
psychiatric disorder (1 paper, 2025). A disorder characterized by behavioral and/or psychological abnormalities, often accompanied by physical symptoms. "Several genes—including ATP6V1B2, FBXO7, PHF23, and WDR6—consistently emerged as risk factors in multiple conditions, suggesting that dysregulation of autophagy-related or immune-modulatory pathways may contribute broadly to the development of inflammatory and psychiatric disorders." (PMID 41595424, 2025).
WDR6 also shares sentences with these, for which no sentence is quoted: acute myeloid leukemia (1 paper); Adrenocortical carcinoma (1); Alzheimer disease (1); blood cancer (1); breast carcinoma (1); B‐Cell Lymphoma (1); CNS cancer (1); colon adenocarcinoma (1); diffuse large B-cell lymphoma (1); Epileptic encephalopathy (1); gastric cancer (1); glioma (1); head and neck squamous cell carcinoma (1); hepatobiliary tumours (1); Insulin resistance (1); kidney cancer (1); lung squamous cell carcinoma (1); lymphoid neoplasm (1); metastatic disease (1); myeloma (1); ovarian carcinoma (1); ovarian serous cystadenocarcinoma (1); Parkinson disease (1); prostate adenocarcinoma (1); sarcoma (1); Skin Cutaneous Melanoma (1); Stomach adenocarcinoma (1); testicular germ cell tumor (1); thymoma (1); Thyroid carcinoma (1).
A further 2 diseases each share a sentence with WDR6 in 1 paper.